Y_RNA (Y RNA )
Gene: Miscellaneous RNA gene on chromosome 7 (138,175,045 to 138,175,136, forward strand). Ensembl gene ENSG00000252820.
Homologues: Orthologues: chimpanzee Y_RNA (100% identical). Paralogues in human: RNY3 (82% identical), Y_RNA (82% identical), RNY3P1 (80% identical), RNY3P4 (80% identical), Y_RNA (80% identical), Y_RNA (79% identical), RNY3P12 (78% identical), Y_RNA (78% identical), Y_RNA (77% identical), Y_RNA (76% identical), RNY3P11 (75% identical), RNY3P14 (75% identical), and 84 more.